HMGB1 (high mobility group box 1)
Diseases named in the same sentence as HMGB1 in open-access papers (continued):
Sharing a sentence is not in itself a finding about the gene and the disease.
bronchiolitis (8 papers, 2020 to 2024). Inflammation of the bronchioles characterized by swelling of the bronchioles and mucus accumulation. "Significantly, the inhibition of MLKL or RIPK1 decreased RSV-induced hAEC cell death and associated HMGB1 release in vitro, and conferred protection against severe bronchiolitis in vivo in a preclinical model." (PMID 35712662, 2022). "It has been clinically shown that the level of HMGB1 in nasopharyngeal aspirates of children with bronchiolitis caused by RSV was significantly higher than that of patients without lower respiratory tract infection and was correlated with clinical severity." (PMID 33140586, 2021). "Bronchiolitis is typically characterised by neutrophilia, oedema, epithelial sloughing, and the release of pro-inflammatory cytokines, such as the alarmin HMGB1." (PMID 35712662, 2022). "The second study reported that neonatal mice deficient in interferon-β promotor stimulator-1 (IPS-1) that were PVM-infected and subsequently re-infected with PVM developed severe bronchiolitis marked by release of HMGB1 and IL-33." (PMID 32397226, 2020). "Notably, the release of HMGB1 due to respiratory syncytial virus-induced necrotizing apoptosis has been identified as a critical factor in viral bronchiolitis." (PMID 39693295, 2024). "In a model of severe bronchiolitis using IRF7-deficienct mice, neonatal infection with PVM led to release of IL-33 and HMGB1 (high-mobility group box 1), another nuclear alarmin, both of which contributed to ILC2 proliferation, type 2 inflammation, and airway remodeling." (PMID 35493465, 2022). "In this study, to determine whether HMGB1 is a contributing factor we used a preclinical model of neonatal viral bronchiolitis." (PMID 32658914, 2020). "Moreover, HMGB1 levels were greater in the NPA of infants hospitalized for severe RSV-induced bronchiolitis." (PMID 32397226, 2020). "Previously, we demonstrated that HMGB1 and necroptosis proteins are upregulated in two preclinical models of bronchiolitis and that RSV infection of human airway epithelial cells (hAECs) induces necroptosis at 24 h post infection (hpi), leading to the release of HMGB1." (PMID 35712662, 2022).
cardiac arrest (8 papers, 2016 to 2022). Cessation of breathing and/or cardiac function. "Serum levels of oxidative stress products (8-iso prostaglandin F2 alpha and MDA) and inflammatory cytokines (TNF alpha, IL-1 beta, and HMGB1) are increased at 3, 12, and 24 h after cardiac arrest." (PMID 36101338, 2022). "Serum HMGB1 for first 24 h after cardiac arrest was significantly correlated with SOFA score, NSE, and IL-6." (PMID 28950909, 2017). "Our study indicates that serum HMGB1 for first 24 h after cardiac arrest significantly correlates with SOFA score, NSE, and IL-6." (PMID 28950909, 2017). "Increasing serum HMGB1 at ROSC means that initial HMGB1 was passively released by necrotic or damaged cells due to cardiac arrest." (PMID 28950909, 2017). "Some pilot studies focused on HMGB1 after cardiac arrest have been done regarding the influence on neurological outcome." (PMID 28950909, 2017). "We evaluated the dynamics of HMGB-1, mitochondrial DNA, and other variables in patients with return of spontaneous circulation after out-of-hospital cardiac arrest." (PMID 27247778, 2016). "We aimed to evaluate HMGB-1 and mitochondrial DNA dynamics and estimate the prognostic value for neurological outcome in patients with post-cardiac arrest syndrome after out-of-hospital cardiac arrest." (PMID 27247778, 2016). "A sequential response of post-cardiac arrest including HMGB1 can be observed in common, regardless of cardiac or noncardiac etiology." (PMID 28950909, 2017). "The influence of serum HMGB1 before and after cardiac arrest could not be completely excluded." (PMID 28950909, 2017). "Therefore, the purpose of this study was to evaluate HMGB-1 and mtDNA dynamics, the relationship between HMGB-1, mtDNA, and severity of conditions and estimate the prognostic values of these molecules in patients with post-cardiac arrest syndrome after out-of-hospital cardiac arrest." (PMID 27247778, 2016). "In the brain 2 h post-ROSC, cardiac arrest and CPR led to an increase in the mRNA levels of IL-6, IL-1β, and TNF-α, but not HMGB-1." (PMID 35011872, 2021).
cholangiocarcinoma (8 papers, 2019 to 2025). A carcinoma that arises from the intrahepatic biliary tree (intrahepatic cholangiocarcinoma) or from the junction, or adjacent to the junction, of the right and left hepatic ducts (hilar cholangiocarcinoma). "In cholangiocarcinoma, HOTAIR suppresses autophagy by modulating the MIR204-5p–HMGB1 (high mobility group box 1) axis, while it regulates autophagy through the MIR20B-5p–ATG7 pathway in hepatic ischemia-reperfusion injury." (PMID 39684286, 2024). "Cisplatin and oxaliplatin, the conventional anticancer chemotherapy drugs, are emphasized as a cause of well-known DAMPs’ release from cholangiocarcinoma (CCA) cells (e.g., HSP family, S100, CRT and HMGB1), whereby they trigger Akt, ERK and Cyclin-D1 to promote tumor activities." (PMID 36142453, 2022).
coagulopathy (8 papers, 2009 to 2023). "Our results showed that platelets from TBI patients, especially those with coagulopathy, were more likely to express HMGB1 than platelets from other groups." (PMID 36802340, 2023). "Early plasma elevations of HMGB1 were also associated with some clinical outcomes, including GCS, ISS, SIRS, blood base deficit, coagulopathy, and fresh frozen plasma and fluid resuscitation requirements." (PMID 35053249, 2022). "Given that PF4 and HMGB1 induce NET formation, PF4+ and HMGB1+ pEVs contribute to NET-associated coagulopathy." (PMID 35874830, 2022). "There is also a proven correlation between plasma levels of HMGB1 and the importance of tissue hypoperfusion and traumatic coagulopathy." (PMID 36726379, 2022). "Plasma levels of HMGB1 correlate with the severity of injury, tissue hypoperfusion, early posttraumatic coagulopathy and hyperfibrinolysis as well with a systemic inflammatory response and activation of complement." (PMID 19887013, 2009). "• Plasma levels of HMGB1 correlate with early post-traumatic coagulopathy and other markers of systemic inflammation." (PMID 19887013, 2009). "Western blots showed the expression of LC3B on neutrophils treated with platelets from TBI patients, especially those with coagulopathy, and these effects could be decreased with Box A (HMGB1 competitive antagonist)." (PMID 36802340, 2023). "However, TBI and CY can mobilize HMGB1 to the PB, and increased levels of HMGB1 correlate with increased PAI-1 after allo-HSCT, inducing transplantation-associated coagulopathy (TAC) conditions such as veno-occlusive disease (VOD)." (PMID 32660524, 2020).
Crohn disease (8 papers, 2011 to 2023). A gastrointestinal disorder characterized by chronic inflammation involving all layers of the intestinal wall, noncaseating granulomas affecting the intestinal wall and regional lymph nodes, and transmural fibrosis. "We have previously shown that high levels of anti-HMGB1 antibodies (abs) in plasma from patients with Crohn’s disease are negatively associated with high fatigue, suggesting a protective/down-regulating role for these specific abs." (PMID 37365509, 2023). "We have previously shown that high levels of anti-HMGB1 abs in patients with Crohn’s disease are associated with less fatigue." (PMID 37365509, 2023). "The main finding of this study is that high levels of anti-HMGB1 auto-Abs in blood are associated with less fatigue in patients with Crohn’s disease." (PMID 33940970, 2021). "We aimed to elucidate how HMGB1 influences fatigue in patients with Crohn’s disease, and how the protein interacts with other candidate biomarkers of fatigue." (PMID 37365509, 2023). "In conclusion, we found that the blood concentration of anti-HMGB1 Abs in patients with Crohn’s disease strongly influences the severity of fatigue." (PMID 33940970, 2021). "We measured Abs against disulphide (ds) HMGB1 and fully reduced (fr) HMGB1 in plasma from 57 patients with Crohn’s disease." (PMID 33940970, 2021).
gastric ulcer (8 papers, 2013 to 2025). An ulcerated lesion in the mucosal surface of the stomach. "Previously, HMGB1 was found to be associated with delayed gastric ulcer healing, and played a role in Helicobacter Pylori-induced inflammation." (PMID 31404064, 2019). "HMGB1 is a proinflammatory mediator linked to the delayed healing of gastric ulcers." (PMID 40563542, 2025). "TNFα overexpression and excessive neutrophil infiltration are important factors in delayed healing of gastric ulcers, while exogenous HMGB1 induces TNFα expression and Myeloperoxidase (MPO) activity." (PMID 39008169, 2024). "Exogenous HMGB1 delays gastric ulcer healing, while immune neutralization of HMGB1 or inhibition of HMGB1 release promotes ulcer healing." (PMID 39008169, 2024). "The main purpose of the current investigation was to evaluate the in vivo anti-inflammatory and anti-ulcerogenic capabilities of BIEE against ethanol-induced gastric ulcers in rats via the HMGB1/TLR-4/NF-B signaling pathway." (PMID 37371993, 2023). "In conclusion, this study is the first to provide evidence to the role of HMGB1 in ethanol-induced gastric ulcer, and the crosstalk of Nrf2, NOXs and HMGB1." (PMID 31404064, 2019). "Taken together, this study is the first to highlight the role of HMGB1 in ethanol-induced gastric ulcer, and correlate it to Nrf-2." (PMID 31404064, 2019). "In conclusion, we have shown that HMGB1 is a complicating factor in the healing process of gastric ulcer as well as in other pathological conditions." (PMID 24244627, 2013). "Collectively, the elevation of serum HMGB1 resulted was due to passive release from injured cells at the gastric ulcer and active secretion from inflammatory cells." (PMID 24244627, 2013). "The complicating effect of exogenous rHMGB1 on gastric ulcer healing was canceled by coadministration of anti-HMGB1 antibody." (PMID 24244627, 2013). "Serum HMGB1 levels increased following the induction of gastric ulcer but declined at the late phase of healing, although the expression of HMGB1 and TNFα remained high." (PMID 24244627, 2013). "In this study, we demonstrated that exogenous HMGB1 delays gastric ulcer healing, while inducing TNFα expression and MPO activity." (PMID 24244627, 2013). "The aim of this study was to evaluate the role of HMGB1 and its receptors in the healing of gastric ulcers." (PMID 24244627, 2013). "Quercetin could enhance gastric ulcer treatment through the Nrf2/HO-1 and HMGB1/TLR4/NF-κB pathways, protecting gastric lesions from ethanol." (PMID 40017602, 2025). "The investigation into the HMGB1/NLRP3/NF-κB signaling pathway revealed significant alterations across the experimental groups, highlighting the inflammatory response associated with gastric ulceration and the therapeutic potential of OMP and OMP-NS." (PMID 40563542, 2025). "The delay of gastric ulcer by HMGB1 is RAGE- and TLR4-dependent." (PMID 39008169, 2024). "So, the current study elucidates for the first time the possible gastroprotective activity of RK against ethanol-induced acute gastric ulceration in rats, in addition, identify the role of HMGB1 in ethanol-induced gastric ulceration, and the crosstalk of Nrf2 with HMGB1 and NOXs." (PMID 31404064, 2019). "Interestingly, ethanol-induced gastric ulcer was associated with Nrf2 downregulation, which was correlated with NOX-1, 2 NOX-4, and HMGB1 upregulation, and was significantly reversed by RK pre-treatment." (PMID 31404064, 2019). "In addition, illustrating the crosstalk of Nrf2 with NOXs, and HMGB1 in ethanol-induced gastric ulcers." (PMID 31404064, 2019). "Thus, it is possible that HMGB1 delays gastric ulcer healing through TNFα-triggered inflammatory responses." (PMID 24244627, 2013). "Thus, we showed that HMGB1 is a complicating factor in the gastric ulcer healing process, which acts through TLR4 and RAGE to induce excessive inflammatory responses." (PMID 24244627, 2013). "The aim of this study was to investigate the role of HMGB1 in gastric ulcer healing." (PMID 24244627, 2013).
gastric ulcer (continued). "We next evaluated whether HMGB1 was involved in gastric ulcer healing." (PMID 24244627, 2013). "Conversely, treatment with OMP or OMP-NS showed significant reductions in HMGB1, NLRP3, NF-κB, and proinflammatory cytokine levels, indicating potential in mitigating inflammation and promoting healing in gastric ulcers." (PMID 40563542, 2025). "The compound has proved its potency as an antiulcer agent towards Ethanol-induced gastric ulcer and the mechanism was possibly elucidated via Nrf2/HO1 and HMGB1/TLR4/NF-κB pathways, along with identification of the relation between them." (PMID 37371993, 2023). "Some studies visualize the role of Nrf2 activation in inhibition of HMGB1 expression in different tissues, but their crosstalk in gastric ulceration was not studied up till now." (PMID 31404064, 2019). "Notably, Nrf2 plays an essential role in regulating the activity of HMGB1, and a previous study on ethanol-induced gastric ulcers demonstrated a negative correlation between HMGB1 and Nrf2 levels." (PMID 40563542, 2025). "However, the role of HMGB1 in ethanol-induced gastric ulcer is not yet elucidated." (PMID 31404064, 2019).
ischemia reperfusion injury (8 papers, 2014 to 2025). Adverse functional, metabolic, or structural changes in ischemic tissues resulting from the restoration of blood flow to the tissue (reperfusion), including swelling; hemorrhage; necrosis; and damage from free radicals. "High-mobility group box 1 has been nominated to be an early mediator of inflammation and organ damage in ischemia-reperfusion injury by increasing production of tumor necrosis factor-α, IL-1, IL-6, and other pro-inflammatory mediators." (PMID 35395776, 2022). "All these effects were blocked by repression of miR-451, suggested that mir-451 plays an important role in the cardioprotection of HMGB1 against ischemia-reperfusion injury." (PMID 32678819, 2020). "GL has a protective effect on ischemia-reperfusion injury in rat brains through the inhibition of inflammation, oxidative stress and apoptotic injury by antagonising the cytokine activity of HMGB1." (PMID 24594628, 2014). "In addition, HMGB1 is an important target in inflammatory processes; it has been shown in models of ischemia reperfusion injury (IRI), e.g., renal IRI, that the administration of an anti-HMGB1 antibody reduces inflammation." (PMID 40868835, 2025).
liver cirrhosis (8 papers, 2010 to 2025). "HMGB‐1 is another molecule associated with cellular damage, and therefore, was also evaluated in patients with compensated vs. decompensated liver cirrhosis, and during follow‐up." (PMID 39533838, 2025). "During follow‐up after TIPS, HMGB‐1 levels gradually increased, ultimately to levels comparable to patients with compensated liver cirrhosis, thus reaching a state of homeostasis." (PMID 39533838, 2025). "Unexpectedly, baseline HMGB‐1 values were higher in patients with compensated liver cirrhosis, compared to those with decompensated liver cirrhosis." (PMID 39533838, 2025). "prepared pPB peptide‐modified and HMGB1‐siRNA‐loaded stable LNPs (HMGB1‐siRNA@SNALP‐pPB) to treat liver cirrhosis effectively." (PMID 39290252, 2024). "Previous studies have shown that transudative effusions resulting from congestive heart failure or liver cirrhosis had significantly lower levels of HMGB1 when compared with exudative effusions arising from infection or malignancy." (PMID 33013860, 2020). "Further studies are warranted to investigate of the role and regulation of HMGB1 in liver cirrhosis and HCC." (PMID 27836008, 2016). "Liver cirrhosis was induced in C57BL/6J mice using carbon tetrachloride (CCl4) injections, followed by HMGB1 peptide treatment." (PMID 40503100, 2025). "We examined the expression of HMGB1 in peritumoral liver tissues from 36 patients with HBV-negative HCC without liver cirrhosis." (PMID 27836008, 2016). "Therefore, we further analyzed the potential roles and prognostic value of HMGB1 and explored the correlation between HMGB1 and macrophage infiltration in patients with HBV-related HCC complicated with liver cirrhosis." (PMID 27836008, 2016). "Ninety-four of the patients had elevated tumoral HMGB1 expression and 59 of the patients had elevated peritumoral HMGB1 expression, compared to only 4 patients with elevated peritumoral HMGB1 expression in 36 pateints with Hepatitis B virus (HBV)-negative HCC without liver cirrhosis (p < 0.001)." (PMID 27836008, 2016).
non-alcoholic steatohepatitis (8 papers, 2017 to 2024). "HMGB1 functions as an inflammatory cytokine, and its inhibition and transport blockage have reportedly prevented non-alcoholic steatohepatitis." (PMID 38034869, 2023). "In nonalcoholic steatohepatitis, elevated Lcn2 induces neuroinflammation through the release of HMGB1, resulting in blood–brain barrier dysfunction." (PMID 36835151, 2023). "A recent report showed that the progression of nonalcoholic steatohepatitis was reduced by inhibiting HMGB1–NF-κB translocation." (PMID 28798347, 2017). "In a methionine and choline deficiency diet (MCDD)-caused nonalcoholic steatohepatitis (NASH) model, CGA increases the biogenetics of mitochondria and suppresses the generation of extracellular matrix triggered by HMGB1 in liver endothelial cells, thus attenuating liver fibrosis." (PMID 38612964, 2024).
peripheral arterial disease (8 papers, 2017 to 2023). A disorder of the arteries supplying the upper and lower extremity and the visceral organs. "A clinical investigation demonstrated that serum HMGB‐1 level was associated with peripheral artery disease in DM patients, whereas the underlying mechanism has still remained elusive." (PMID 33724642, 2021). "HMGB1 plays an important role even in peripheral arterial disease and its severity; in fact, diabetic patients with limb ischemia had higher HMGB1 serum levels with respect to those with stable peripheral arterial disease." (PMID 34044825, 2021). "Furthermore, in a diabetic population, higher levels of HMGB1 and osteoprotegerin, a member of the tumor necrosis factor (TNF) receptor superfamily, have been associated to peripheral arterial disease." (PMID 34044825, 2021). "Moreover, cilostazol, a drug commonly used in peripheral arterial disease, is able to inhibit the secretion of HMGB1 and to reduce the volume of carotid atherosclerotic plaque." (PMID 34044825, 2021). "Similar to our study, several in vivo studies using HMGB1 have showed that HMGB1 can induce angiogenesis through VEGF in ischemic tissue, such as peripheral artery disease and acute MI." (PMID 32275672, 2020). "The aim of this study was to investigate the potential role of HMGB-1, OPG and several inflammatory mediators such as C-reactive protein (HsCRP), tumor necrosis factor-alpha and interleukin-6 (IL-6) on the presence and severity of peripheral artery disease in patients with T2D." (PMID 28789654, 2017).